RNU7-124P (RNA, U7 small nuclear 124 pseudogene)
Gene: Small nuclear RNA gene on chromosome 9 (37,936,707 to 37,936,768, reverse strand). Ensembl gene ENSG00000251745.
Homologues: Orthologues: macaque U7 (90% identical). Paralogues in human: RNU7-7P (89% identical), RNU7-28P (87% identical), RNU7-154P (85% identical), RNU7-35P (85% identical), RNU7-57P (85% identical), U7 (85% identical), RNU7-113P (84% identical), RNU7-11P (84% identical), RNU7-13P (84% identical), RNU7-167P (84% identical), RNU7-176P (84% identical), RNU7-25P (84% identical), and 141 more.